RAG2 (recombination activating 2)
Diseases named in the same sentence as RAG2 in open-access papers (continued):
Sharing a sentence is not in itself a finding about the gene and the disease.
colitis (continued). "In addition, it has been documented that intestinal Il-1β and Il-17A produced by ILCs play an important role in the development of Hh-induced colitis in RAG2 mice." (PMID 33255175, 2020). "The Klebsiella pneumoniae and Proteus mirabilis were also detected in T-bet(-/-)×Rag2(-/-) ulcerative colitis (TRUC) mice, and these TRUC-derived communities could trigger colitis in both Rag2(-/-) and WT mice." (PMID 31354859, 2019). "The aHPD did not change the number of regulatory T cells or Th17 cells and still worsened the colitis in immuno-deficient RAG2 knock-out mice suggesting that this effect was not dependent on adaptive immunity." (PMID 31105710, 2019). "Similarly, Klebsiella pneumoniae and Proteus mirabilis, when overabundant in a T-bet-Rag2 mice model, were correlated with the degree of severity of colitis." (PMID 31412603, 2019). "Similarly as immune-competent BALB/c mice, aHPD-fed RAG2−/− mice are more sensitive to acute colitis." (PMID 31105710, 2019). "We used the RAG2-/- T cell transfer colitis model and the VILLIN-HA T cell transfer model." (PMID 28938014, 2017). "IL-6Rα-deficient CD4+ CD45RBhi T cells failed to induce colitis when transferred into RAG2 KO mice and compared to WT mice, IL-6RαT-KO mice were also resistant to the induction of EAE following immunization with MOG35-55/CFA." (PMID 24842874, 2014). "When colonic LP cells of n = 9 mice of both groups were systematically analysed at 12–13 days post colitis induction, substantially reduced numbers of various cell subsets could be seen in Trem1−/− x Rag2−/− mice." (PMID 24453980, 2014). "In contrast, when naïve T cells were co-transferred with TRAF6-/-Tregs, Rag2-deficient mice showed colitis (naïve T+cKO Treg) like without Tregs (naïve T cell alone)." (PMID 24058613, 2013). "To determine whether the Mst1 deficiency altered Foxp3+ Treg cell functions, we employed the experimental colitis model induced by adoptive transfer of naïve T cells into Rag2-/- mice." (PMID 24040101, 2013). "In addition to the role of IFN-γ in T cell mediated disease, IL-23 dependent innate colitis induced by H. hepaticus infection of 129SvEv.Rag2−/− mice is inhibited by blockade of IFN-γ." (PMID 23200826, 2012). "Indeed, CD4+ T cells with reduced levels of CARS2/CPERS exhibited accelerated cell cycle entry and induced severer colitis in Rag2-/- mice, and treatment with GSSSG, an endogenous donor of supersulfide that is generated by CARS2/CPERS, ameliorated inflammation." (PMID 40303402, 2025). "Next, to test whether there was any defect when transferred to an inflammatory environment, we performed transfer colitis experiments, analyzing control or Itgb8 KO Treg cells transferred to colitic Rag2−/− mice that had received naive CD4+ T cells 2 weeks earlier." (PMID 25979421, 2015). "The most popular models of colitis include chemical induction (oxazolone, TNBS, DSS), adoptive T‐cell transfer in SCID or RAG2‐/‐ mice, IL‐10 knockout mice, and the SAMP1/YitFc mouse strain (spontaneous colitis model)." (PMID 40457749, 2025). "In accordance with the contrasting effect of LysoPS on these colitis models, the number of IFN-γ–producing CD4+ T cells in the large intestine was substantially increased in Rag2−/− mice that received naive CD4+ T cells compared with DSS-treated mice." (PMID 35608941, 2022). "Interestingly, cohousing wildtype mice with IL-22–deficient mice increased the severity of DSS-induced colitis in these wildtype mice, suggesting that the colitis might be ‘transmissible’ as has been shown for TRUC mice (mice that are deficient for both T-bet and Rag2)." (PMID 34603258, 2021). "H&E staining further confirmed reduced inflammation in 3PO-treated Rag2–/– mice, indicating that 3PO-mediated amelioration of colitis does not require the adaptive immune system." (PMID 41378888, 2026). "In the absence of iTreg injection, recipient RAG2−/− mice developed colitis and reduced body weight (open circles)." (PMID 32655569, 2020).
colitis (continued). "Male-biased promotion of Hh colitis coinfected with Hp in RAG2 mice in the current study is not in agreement with previous findings on effect of Hp infection on bacterium- or chemically induced colitis in female C57BL/6 mice." (PMID 33255175, 2020). "Overall, T-bet deficiency caused increased NKp46- CCR6- ILC3 and ILC2 cellularity in Rag-sufficient mice, but not at the cost of spontaneous colitis as observed in H. thyphlonius-infected Rag2-/-xTbx21-/- mice." (PMID 33603753, 2020). "Since aggravated colitis in DKO mice was ameliorated with broad-spectrum antibiotics, and thus clearly depended on the gut microbiota, we sought to determine the differences in the composition of the gut microbiome between Rag2-/- and DKO mice." (PMID 27050757, 2016). "We showed that contrary to Rag2-/- mice, in which adoptive transfer of naïve CD4+CD45RBHi T cells requires typically 6–8 weeks for the development of moderate disease, T cell-transferred DKO mice developed rapidly progressive colitis in less than two weeks." (PMID 27050757, 2016). "With the exception of modest, but significant increase of mucosal TNFα expression, 13 days post-transfer Rag2-/- mice did not develop overt signs of colitis." (PMID 27050757, 2016). "To determine whether the protective effect of 3PO on colitis is independent of the adaptive immune system, we administered 3PO to Rag2–/– mice, which lack T and B cells." (PMID 41378888, 2026). "To investigate the effects of B/T/ILCs in liver injury‐aggravated colitis, we administrated CCl4, along with or without NMN supplementation, to mice lacking T and B cells (Rag2–/–) or those deficient in T, B cells, and ILCs (Rag2–/–Il2rg–/–), followed by DSS feeding." (PMID 39119946, 2024). "Transfer of Tbx21–/– naïve CD4+ T cells into Rag2–/– mice gives rise to a higher proportion of IL‐17A‐producing CD4+ T cells and more severe colitis compared to mice receiving WT naïve CD4+ T cells, suggesting that T‐bet restrains pathology in IL‐17‐driven colitis." (PMID 35092032, 2022). "Using this approach, we tested the capacity of MP cell subpopulations to induce colitis by individually transferring CD127hi Sca1lo, CD127hi Sca1hi, CD127lo Sca1hi, and CD127lo Sca1lo Foxp3− MP CD4+ T cell subsets from Foxp3-reporter mice to Rag2 KO recipients." (PMID 35707543, 2022). "RAG-2−/− LP CD4+ mice exhibited severe colitis without infiltration of T cells in the liver." (PMID 24392145, 2014). "It is possible that IL-7R expression by cells other than CD4+ T cells has a modest effect in their model as they noted a trend of increased colitis scores in IL7R−/− x Rag2−/− recipients of wildtype naïve T cells compared to Rag2−/− -only recipients, although these differences were not significant." (PMID 23057802, 2012). "CD4+CD25− effector T cells from colitic Gαi2−/− mice (KO-Teff), or CD4+CD25− effector T cells from WT mice (WT-Teff) were transferred with or without CD4+CD25+ Treg from Gαi2−/− mice with colitis (KO-Treg) or WT mice (WT-Treg) at a 4∶1 Teff∶Treg ratio into RAG2−/− recipients." (PMID 21966415, 2011). "Rag2-/-xγc-/- mice lack mature ILC, thus indicating that these cells drive colitis in the absence of an adaptive immune response." (PMID 34795671, 2021). "Using adoptive transfer studies in RAG2 KO recipient animals, we confirmed that CD8+ T cells rather than CD4+ T cells are the relevant colitis effector cells in Yeti mice." (PMID 33513946, 2021). "In contrast, Rag2-/-xγc-/- mice lacking both mature ILC and adaptive immune response cells were very resistant to developing colitis and the additional germline deletion of T-bet in Rag2-/-xγc-/-xTbx21-/- did not change the course of colitis." (PMID 34795671, 2021). "ILCs were isolated from colons of Tbx21-/- × Rag2-/- mice (TRUC), which develop colitis; patients with inflammatory bowel disease (IBD); and patients without colon inflammation (controls)." (PMID 25917784, 2015).
colitis (continued). "The RAG-2−/− LP CD4+ mice showed almost no CD3+CD4+ T cell infiltration in the liver, but did exhibit severe colitis with marked infiltrations of CD3+CD4+ T cells in the colon." (PMID 24392145, 2014). "Compared to similarly aged, non-colitic Rag2 knockout mice, the isotype-treated TRUC mice with colitis displayed a trend (p = 0.07) towards lower hepcidin levels, while anti-TNFα treatment of the TRUC mice led to a significant increase in hepcidin." (PMID 22675442, 2012). "In addition, in a non-infectious colitis model in Rag2-/- mice, where CD40 stimulation induced innate immune cell-mediated colitis, adoptive transfer of Tregs from wild-type mice reduced colitis severity and tissue damage, but Tregs from Gpr15 KO mice failed to do so." (PMID 37457732, 2023).
Immunodeficiency (50 papers, 2006 to 2026). Failure of the immune system to protect the body adequately from infection, due to the absence or insufficiency of some component process or substance. "In humans, RAG2 deficiencies are linked to the Omenn syndrome, a severe immunodeficiency with clinical symptoms such as erythematous rash, hepatosplenomegaly, desquamation, alopecia and susceptibility to recurrent infections." (PMID 38969989, 2024). "Mutations in the recombination activating gene 1 (RAG1) and RAG2 in humans are associated with a broad spectrum of clinical phenotypes, from severe combined immunodeficiency to immune dysregulation." (PMID 37475856, 2023). "In humans, mutations in RAG1 or RAG2 result in various degrees of residual V(D)J recombination activity, causing a broad spectrum of clinical phenotypes, ranging from severe combined immunodeficiency to autoimmunity." (PMID 36326898, 2022). "The rag2 is strongly involved in immune system development; its human ortholog is linked to Omenn syndrome and severe combined immunodeficiency." (PMID 34281170, 2021). "Hypomorphic RAG1 and RAG2 mutations, responsible for residual V(D)J recombination activity (on average 5–30%), result in a distinct phenotype of combined immunodeficiency with granuloma and/or autoimmunity (CID-G/A)." (PMID 31388879, 2019). "The R229Q mutation of Rag2 is well described in patients leading to severe immunodeficiency with T−B−SCID or OS5,8,12." (PMID 30872621, 2019). "An immunological disorder exemplifying this challenge occurs through damaging mutations in RAG1 and RAG2 which presents at an early age with a distinct phenotype of life-threatening immunodeficiency or autoimmunity." (PMID 31388879, 2019). "Since the expression of RAG proteins is restricted to immature lymphocytes, the long-term effect of R229Q mutation on lymphocytes of Rag2 KI/EGFP mice can lead to severe immunodeficiency." (PMID 30872621, 2019). "RAG1 or RAG2 mutations are associated with defects in V(D)J recombination activity, causing severe immunodeficiency with a wide spectrum of clinical phenotypes." (PMID 30872621, 2019). "Nonsense mutations inRAG1/RAG2 cause the most profound immunodeficiency syndrome, severe combined immunodeficiency (SCID)." (PMID 30800289, 2019). "Rag2 and IL2rg mutations cause immune system disorders associated with T-, B-, and NK cell function and some cytokine activities." (PMID 31134127, 2019). "In both thymoma and immunodeficiency caused by RAG1 or RAG2 mutations, thymic deficiency of AIRE has been documented." (PMID 29651287, 2018). "The deletion of Rag2 gene causes immune deficiency in mice, and plays a role in the deregulation of many other important genes and miRNAs that are involved in other physiological processes." (PMID 29495457, 2018). "In line with the NCBI data, 51.64% (110 out of 213) of the total number of mutations in cases with immunodeficiencies or autoimmunity had CpG mutations mediated by methylation in RAG1 coding sequence compared to 28.86% (28/97) in RAG2 coding sequence (z score = 3.74, p value = 0.0002)." (PMID 38240953, 2024). "Gene mutations could additionally cause a variety of immune dysfunctions, with prkdc and Rag2 spontaneous gene mutations having resulted in SCID mice." (PMID 31134127, 2019). "RAG1 and RAG2 mutations in humans are associated with a broad spectrum of clinical and immunological phenotypes, including T− B− severe combined immune deficiency (SCID), Omenn syndrome (OS), atypical SCID (AS), and combined immune deficiency with granuloma and/or autoimmunity (CID-G/A)." (PMID 28769923, 2017). "Rats with knockout of the Il2rg and Rag2 genes exhibit significant immunodeficiency, characterized by a reduction in WBC counts and hypoplasia of the spleen and thymus, which are hallmark features of a SCID phenotype." (PMID 39731164, 2024).
Immunodeficiency (continued). "These mice were generated by mating NRG mice possessing a genetic defect (Rag2/Il2rg) conferring immunodeficiency, and Alb‐rtTA/TRE‐uPA mice capable of producing endogenous liver damage in the presence of doxycycline." (PMID 37864397, 2024). "Then, this study inspected published clinical cases with immunodeficiencies and found that 51.6% and 28.86% of patients with RAG1 and RAG2 mutations, correspondingly, had CpG methylation-mediated mutagenesis (p-value=0.0002)." (PMID 38240953, 2024). "The immunodeficiency phenotype was preliminarily confirmed by the presence of severe thymic hypoplasia in Il2rg-single knockout (sKO) and Il2rg/Rag2-double knockout (dKO) rats." (PMID 35960733, 2022). "Immunodeficiency was preliminarily confirmed by the presence of severe thymic hypoplasia in Il2rg-sKO and Il2rg/Rag2-dKO rats, whereas thymic morphology was similar between double heterozygous mutant female rats and WT female rats." (PMID 35960733, 2022). "The immunodeficiency phenotypes exhibited by Il2rg-sKO and Il2rg/Rag2-dKO rats were comparable to the phenotypes of our previously developed immunodeficient rat models." (PMID 35960733, 2022). "All cloned RAG1, RAG2, and IL2RG mutated piglets were raised in the conventional housing environment and piglets with immunodeficiency presented health issues." (PMID 31253764, 2019). "To establish a murine model of severe immunodeficiency with SCID or OS, we generated a Rag2 knock-in mouse carrying the R229Q mutation by CRISPR/Cas9-mediated gene editing." (PMID 30872621, 2019). "While Rag2 KI/EGFP mice recapitulate human OS13, we initially expected that our Rag2 KI mice will give rise to an immunodeficiency characterized by SCID or OS." (PMID 30872621, 2019). "Adding to our knowledge of ACAAs in immunodeficiency, we recently discovered high titer type I IFN ACAAs in RAG1 and RAG2 mutation-associated immunodeficiencies." (PMID 29651287, 2018). "The macrofilaricidal efficacy of both OXF and FBZ was reduced in all tested immunodeficient strains, and treatment efficacy was lowest in strains with more severe immunodeficiency, i.e., IL-4r/IL-5−/− vs. ΔdblGata1 mice, or completely abrogated in Rag2/IL-2rγ−/− mice." (PMID 37440891, 2023). "However, homozygote rag2 mutants exhibited a less severe immunodeficiency, with a strong decrease in mature T cells, but with B cells only moderately affected." (PMID 35216498, 2022). "RAG2 severe combined immune deficiency (RAG2-SCID) is a lethal disorder caused by the absence of functional T and B cells due to a differentiation block." (PMID 31956083, 2020). "Thus, Rag2/IL2rg-/- knockout mice possessed features of severe combined immunodeficiency (SCID), which is an ideal model for human xenograft." (PMID 31134127, 2019). "Furthermore, given their prevalence in APS-1, RAG1/RAG2-associated immunodeficiencies, SLE, and now IPEX, it will be important to consider type I IFN ACAAs as potential diagnostics and biomarkers both in immunodeficiency and autoimmunity." (PMID 29651287, 2018). "Rag2-/γ chain-/C5- mice have a more profound immunodeficiency than the mdx nude mouse, while the latter is dystrophin deficient and its muscles exhibit pathological features, such as muscle degeneration and regeneration, accompanied by the infiltration of inflammatory cells." (PMID 25949786, 2015). "Recently, Severe Combined Immunodeficiency (SCID) rats were generated using CRISPR/Cas9 system, targeting Il2rg and Rag2 in National BioResource Project in Japan." (PMID 39731164, 2024). "However, the degree of immunodeficiency affects engraftment rates, and strains of mice with the most severe immunodeficiencies typically have the highest engraftment rates, such as NMRI nude mice, Bl6/Rag2/GammaC double knockout, or CD-1 mice." (PMID 35664756, 2022).
Immunodeficiency (continued). "If the lower ectotherm RAG2 such as zRAG2 did not evolve, endothermic jawed vertebrates such as mice would have not only had weaker recombination efficiency and immunodeficiency but also developed severe cachexia syndromes." (PMID 32139788, 2020). "The Rag2/IL2 gene mutation did not affect the normal physiological behavior of mice, but the mutated mice displayed the typical characteristics of immunodeficiency." (PMID 31134127, 2019). "To design the human disease model mimicking severe immunodeficiency, we generated Rag2-R229Q knock-in mice without an epitope tag." (PMID 30872621, 2019). "Interestingly, the strain with the most severe immunodeficiency (Rag2/IL-2rγ−/−) displayed no reduction of the adult worm burden after treatment at all." (PMID 37440891, 2023). "In RAG2−/− mice, endothelial regeneration appeared to be enhanced at baseline compared to wild-type mice, which can be explained by the absence of pro- and antiatherogenic influences due to their immunodeficiency." (PMID 31980946, 2020). "Besides, Rag2 KI mice did not lead to a severe immunodeficiency with T−B− SCID or T+B− OS." (PMID 30872621, 2019).